RNU2-49P (RNA, U2 small nuclear 49, pseudogene)
Gene: Small nuclear RNA gene on chromosome 5 (115,774,319 to 115,774,502, reverse strand). Ensembl gene ENSG00000222598.
Homologues: Orthologues: chimpanzee U2 (99% identical), macaque U2 (93% identical), dog U2 (86% identical), rat LOC120101398 (79% identical). Paralogues in human: U2 (88% identical), U2 (87% identical), RNU2-2 (86% identical), RNU2-3P (85% identical), RNU2-52P (84% identical), RNU2-4P (84% identical), RNU2-6P (82% identical), RNU2-48P (81% identical), RNU2-17P (80% identical), RNU2-26P (80% identical), RNU2-23P (80% identical), RNU2-25P (80% identical), and 66 more.